IL10 (interleukin 10)
Diseases named in the same sentence as IL10 in open-access papers (continued):
Sharing a sentence is not in itself a finding about the gene and the disease.
cancer (continued). "IL‐10 and TGF‐β are regulatory cytokines with a pivotal role in immune tolerance in allergy field whereas promoting cancer growth and progression." (PMID 35344301, 2022). "Clinically, the increase in IL-6 and IL-10 on PTX administration is correlated with joint pain and fatigue respectively in cancer patients." (PMID 35273508, 2022). "In this study, elevated [K+]e by necrotic cancer and cancer-infiltrating cells in the TME increased the expression and production of IL-10 and IL-8 in THP-1-derived M2 macrophages." (PMID 35955737, 2022). "Further, macrophage-mediated phagocytosis is a slow process that not only takes days to complete but is also inhibited by IL-10 and CD47 and PD-L1, two immune checkpoints on cancer cells." (PMID 35856032, 2022). "HSP70 is actively released as exosome surface protein under the stimulation of high levels of IL-10 and IFN-γ in the serum of cancer patients, suggesting the role of exosomal HSP70 in tumor immunity and the potential of HSP70 as a cancer biomarker." (PMID 35757760, 2022). "Although the mean expression levels of IL6, CXCL8, IL10, and IL17A were higher in the cancer group than those in the control group, the difference was not statistically significant." (PMID 36501012, 2022). "In this regard, ICBs and various inhibitors such as indoleamine 2,3-dioxygenase (IDO), interleukin-10 (IL-10), and transforming growth factor-β (TGF-β) are widely used for combination cancer immunotherapy." (PMID 36145656, 2022). "Apart from miR-382, STAT3 was also regulated by miR-1246, IL-6, IL-10, nuclear factor kappa-B p65, or ERK and promoted M2-type macrophages in the progression of carcinoma." (PMID 35585990, 2022). "Immune-suppressive cytokines such as TSLP (thymic stromal lymphopoietin), TGFβ, IL-10, and INOS were often found to be elevated in HH-hyperactivated cancers." (PMID 34831357, 2021). "Of this panel of myokines, their data suggested that IL-10 and OSM are possible candidates mediating the effects of exercise on (breast) cancer cell proliferation." (PMID 33864493, 2021). "Our findings clearly identify an unprecedented crosstalk mechanism between cancer cells and macrophages involving NAA, which acts synergically with IL‐10 and Gln deprivation to polarize macrophages toward a high‐GS, “M2‐like” phenotype." (PMID 34260142, 2021). "As reported, CD44 expression level is positively correlated with PD-L1, PD-1, IL10, and TGFB1 expression in some cancers." (PMID 35187044, 2021). "Glutamine addiction elicits a crosstalk mechanism whereby cancer cells release N‐acetylaspartate (NAA) which, through the inhibition of the NMDA receptor, and synergistically with IL‐10, enforces GS expression in macrophages." (PMID 34260142, 2021). "In particular, IL6, IL10, IL13, VEGF, and TGF-β are secreted by TME inflammatory elements and cancer cells during PC." (PMID 34205944, 2021). "The M2 macrophages produce nutritional polyamines, anti-inflammatory factors (IL-10 and TGF-β), and chemokines (CXCL18 and CXCL22), which play a tumorigenic role in cancer." (PMID 34034714, 2021). "M2 macrophages secrete IL‐10 and TGF‐β, inhibit inflammation, and have many cancer‐promoting functions." (PMID 33949150, 2021). "Cancer cells can also signal to the immune predators in the tumor through expression of immune checkpoints on the cancer cells, such as PD-L1 and CTLA4, or through secretion of soluble immunosuppressive factors, such as TGF-β, IL-10, and soluble WNTs." (PMID 34703824, 2021). "Analysis of cytokines showed that the IL10 and TGFB1 (TGFβ) were overexpressed in EMT-high tumors of most cancer types, and both of these are known to suppress antitumor immunity in TIME." (PMID 35096592, 2021). "We therefore analyzed the expression of mRNA for CD117 and the M2 markers IL-10, fibronectin-1 (FN1), and arginase 1 (ARG1) in total leukocytes from cancer patients and HDs." (PMID 34090509, 2021).
cancer (continued). "Several cytokines such as IL-6, IL-10, TGF-β, TNF-α, and Nodal can regulate the chemoresistance of cancer cells." (PMID 33754002, 2021). "We selected the eleven cytokines that were significantly increased in cancer (GMCSF, IL-6, IL-1β, Rantes/CCL5, MIP1α, MIP1β, TNFα, MCP1/CCL2, IL-8, IL-12p40, IL10) and selected all the positive Pearson's correlations with r > 0.8 and significance of p < 0.01." (PMID 35048057, 2021). "Remarkably, cancer cells enrich the environment with immune suppressive factors and cytokines, such as VEGF, IL-10 and TGF-β, which can either induce tDCs or hamper the maturation of DCs." (PMID 34571894, 2021). "In our pan-cancer analysis, we found a strong and significant correlation between inflammatory (IL6, CXCL8, IL12, TGFβ) and suppressive cytokines (IL10) with EMT score." (PMID 35096592, 2021). "On the other hand, TH2 cytokines IL-10, IL-4 and TGF-β from TH2 cells can promote dissemination of cancer cells dissemination and metastasis in various cancers." (PMID 34012451, 2021). "In conclusion, our study not only illustrates how nivolumab-induced IL-10 production may shape the T cell responses via modulating multiple downstream signaling pathways, but also provides a rationale for the combination of targeting IL-10 and PD-1 for cancer patients." (PMID 34769278, 2021). "The up‐regulation of IL‐4, IL‐5 and IL‐10 as seen in our MRMT‐1/Luc2‐bearing animals is in agreement with previous data and is indicative for cancer physiology modulation." (PMID 31724155, 2021). "HH/GLI1 signaling regulates immune checkpoint modulators such as PD1, CTLA-4, TIM3, LAG3, TIGIT, and IL-10 in exhausted T cells as well as PD-L1/2, CD80/86, OX40L, CD137L, IDO, and CCL22 in cancer cells." (PMID 34831357, 2021). "Our data indicate that muscle-derived CXCL1, IL10 and CCL4 are part of the mechanistic link between exercise and the induction of apoptosis in cancer cells." (PMID 34359731, 2021). "Interestingly, in our cohort of patients, the plasmatic level of IL-10 was correlated with the c-Met expression on monocytes, suggesting that this subset could be involved in IL-10 production in cancer patients." (PMID 34771724, 2021). "The results reveal different networks in each group with IL-10 and Rantes/CCL5 clusters on control samples and GMCSF and IL-6 in cancer." (PMID 35048057, 2021). "EPCs in cancer produce reactive oxygen species (ROS), transforming growth factor β (TGF-β), interleukin-10 (IL-10) and express programmed death-ligand 1 (PD-L1) and potently suppress T-cells." (PMID 33669537, 2021). "We found statistically significant increased mRNA expression of M2/TAM markers IL-10, Vegfa, Tnfα, Fpn1, and Ym1, as well as decreased expression of Nos2 (“iNOS”) in BMDM exposed to conditioned media from Dek expressing cancer cells compared to controls." (PMID 32708944, 2020). "Other molecules described to be expressed in neutrophils in the cancer niche are MMP-9, IL-4, and IL-10 (although very controversial)." (PMID 32117288, 2020). "These IL-10+IL-17+IFN-γ+ Tregs can confer immunotherapy resistance and poor survival in cancer patients." (PMID 33114183, 2020). "A740003 not only inhibited IL-10, IL-6 and monocyte chemoattractant protein-1 (MCP-1) release from macrophage, but also reduced cancer antigen presentation and cancer cell proliferation." (PMID 32280302, 2020). "Our results, along with the findings of other authors, indicate the ability of the CV extract to induce the production of many cytokines, including IL-1β, IL-2, IL-6, IL-10, TNF-α, and IFN-γ, by immune cells and cancer cells." (PMID 33260615, 2020). "We recently reported IL-5, IL-10, IL-6, CxCL-10, and TGF-β elevation in both participants with EpKS and EnKS when compared to KSHV-infected asymptomatic controls prior to cancer therapy." (PMID 32560243, 2020). "It has been reported that IL-10 can regulate proliferation, invasiveness, and EMT by activating STAT3 signaling in other malignant tumors." (PMID 33372604, 2020).
cancer (continued). "Other studies suggest that IL-10 stimulates the EMT process and increases proliferation in cancer cells via a STAT3-NF-κB-IL-10 signaling axis." (PMID 32222879, 2020). "Firstly, by cell to cell contact through CD47 (cancer cell) and SIRPα (macrophage) binding, CCR2, or CX3CR1 chemokine receptors; Secondly, through soluble factors or exosomes loaded in IL-10." (PMID 32477352, 2020). "Production of IL-10, IL-17 and TGF-β by T cells was increased in thepresence of either normal- or cancer-ASCs; however, significant effect was only observed in the IL-10 and TGF-β ofcancer-ASCs (P<0.05)." (PMID 31721539, 2020). "In cancer, regulatory cytokines in the TME such as IL-10 and TGF-β support tumor development by suppressing antitumor immunity in cancer." (PMID 32719682, 2020). "In contrast, a decrease in IL-10 level boosts cellular immunity, which is vital not only in the context of URTI prevention but also for cancer control." (PMID 30770758, 2019). "Inflammatory mediators such as tumor necrosis factor-alpha (TNF-α), Interleukin-6 (IL-6), Interleukin-10 (IL-10) and transforming growth factor-beta (TGF-β) play important roles in tumorigenesis and the development of cancer in different entities." (PMID 31077235, 2019). "On the front of cancer cells, both TMZ-R and TMZ-S cells showed a significant increase in the M2 cytokines mRNA level of IL-10, IL-4, IL-13 and CCL2 as compared to their parental counterparts." (PMID 31462285, 2019). "Cytokine-based immunotherapies such as IL-2 family, IL-10, IL-12, TGF-β, and several other immunosuppressive cytokines are currently under ongoing clinical trials for cancer treatment." (PMID 32117199, 2019). "mPD-L1/mPD-1 can be induced by multiple inflammatory cytokines in cancer, including IFN-γ, IL-6, IL-10, IL-17 and TNF-α." (PMID 30506460, 2019). "It reduces immunosuppression and provides anticancer immunity to fight cancer by reducing the level of TGF-β1 and IL-10." (PMID 30871059, 2019). "Activation of CAFs is induced by cancer-secreting cytokines such as TGF-β, sonic hedgehog (SHH), TNF-α, IL-6, and IL-10." (PMID 30987642, 2019). "The effect of IL-10 and TGF-β therefore most likely depends on the specific cancer type, and therapy targeting these cytokines should be done with careful considerations." (PMID 31134056, 2019). "The activation of the ICOS pathway plays a key role in activating the expansion of Treg and the release of IL-10 by secretion from memory CD4+ T cells, both of which create an immunosuppressive environment for cancer growth." (PMID 31143539, 2019). "Cancer control group (CC) possessed relatively high secretion of IL-6, IFN-γ, MCP-1, IL-10, IL-12p70 and TNF-α from week 1 until week 4 compared with other groups." (PMID 30947706, 2019). "Finally, IL10 plays a dual, controversial role in cervical carcinogenesis; even if IL10 mRNA and/or protein are enhanced in several types of human cancer (including cervix), other works report that higher levels of IL10 may prevent cervical neoplasia by assisting in the elimination of HPV." (PMID 30622662, 2018). "Strategies like the introduction of anti-cancer cytokines (IL12), manipulation of the immune checkpoint signaling (PD1/CTLA4), immunosuppressive soluble factors (TGF-β, IL10), and suppressive surveilling immune cells are aspects worth to be explored." (PMID 29433552, 2018). "Other parameters such as the presence of myeloid derived suppressor cells, levels of Th2 cytokines (for example IL-10) and of indoleamine 2,3-dioxygenase (IDO) can also limit anti-cancer immune responses to therapy blocking PD-1/ PD-L1." (PMID 29843813, 2018). "However, once the lesions had advanced, Treg and IL-10 levels increased in the wildtype but not the IL-23R KO mice, suggesting that at the later stages, Th17 cells could be contributing to the cancer–associated immune suppression." (PMID 29664967, 2018).
cancer (continued). "In cancer cells STAT-3 is often constitutively active, leading to the upregulation of VEGF and IL-10 and concomitant inhibition of DC maturation and function." (PMID 30477198, 2018). "Several inflammatory mediators, such as, IL-6, IL-10, and TGF-β, have been shown to be involved in both the initiation and progression of cancer." (PMID 29783672, 2018). "Remarkably, IL-6, IL-10, CXCR4, and CCL2 mRNA, which are all STAT3 target genes involved in cancer progression, were increased in macrophages exposed to exosomes." (PMID 29867925, 2018). "The expression of Arg-1, IL-10, and VEGF in intratumoral macrophages in HSC-NOG-hIL-6 Tg mice suggests similarities with TAMs in cancer patients, and that they mediate immunosuppression in tumors." (PMID 29456539, 2018). "Therefore we quantified the amount of some pro-inflammatory cytokines (IL1β, TNFα, IL12-p70, IL6, IL8, IL10) by CBA and found that the SCM was highly enriched in IL6 and IL8, two pleiotropic pro-inflammatory cytokines that have been implicated in cancer progression." (PMID 28472950, 2017). "Cancer cells suppress the functions of effector T cells by producing immunosuppressor cytokines TGF- β, IL-6, CCL2 and IL-10." (PMID 28724377, 2017). "IL-10 production from CD25 Tregs, regulates chronic infection and immune response, thereby preventing inflammation-induced cancer." (PMID 28275390, 2017). "Metformin treated cancer cells increased macrophage expression of M1-related cytokines IL-12 and TNF-α and attenuated M2-related cytokines IL-8, IL-10, and TGF-β expression." (PMID 28157701, 2017). "The aim of this study was to compare serum and peritoneal fluid concentrations of sHLA-G, IL-10 and TNF-alpha in women with selected ovarian pathologies: benign serous cysts, endometrioma and malignant tumors." (PMID 28376925, 2017). "Ten healthy adults and 45 cancer patients were analyzed for gene expression of PD-1, CTLA-4, CD25, CD28, IL-10, TGF-β and Foxp3 in peripheral blood." (PMID 28881603, 2017). "The model includes dendritic and cancer cells, CD 4+ and CD 8+ T cells, MDSC cells, interleukins IL-12, IL-2, IL-6, IL-10 and TGF- β, PD-1 and PD-L1, and the two drugs: BRAF/MEK inhibitor (with concentration γB) and PD-1 inhibitor (with concentration γA)." (PMID 28724377, 2017). "Messenger RNA expression of IL-10 and TGF-β1 in ADSCs from patients with cancer was higher than those isolated from healthy patients." (PMID 29104428, 2017). "Previous studies have demonstrated that IL10 acts as a suppressor of the immune system, and an activator of the JAK/STAT3 pathway in cancer cells." (PMID 26956044, 2016). "According to the results, a statistically significant increase of IL-2, IL-10, TNF-α, IFN-γ, and IL-17 was observed in patients with cancer compared with the control group." (PMID 26905729, 2016). "Immune-suppressive activity of IL-10 and TGF-β limits both cancer-promoting inflammation and anti-cancer immunity." (PMID 31051015, 2016). "We demonstrated that introduction of human MUC1 into the IL-10 knockout mouse accelerated the occurrence of IBD, induced a more severe grade of inflammation, and promoted cancer development and progression in over 80% of the mice." (PMID 27754373, 2016). "We have PEGylated recombinant murine IL-10, (PEG-rMuIL-10), and human IL-10 (AM0010), to improve their pharmacokinetic profiles for the purposes of treating cancer patients." (PMID 27299860, 2016). "Cancer patients expressed higher mRNA levels of the M2 polarization markers CD163, ARG1 and IL-10 in CD11b+ cells and increased levels of the M2 cytokines IL-10 and CCL20 in plasma." (PMID 26840567, 2016). "It seems likely that cancer cells, including NPC cells, commonly regulate immune suppression by stimulating IL-10 production in DCs." (PMID 25402728, 2015). "The suppressive functions of IL-10-producing T2-MZP B cells have since been confirmed in a variety of immune-mediated pathologies ranging from autoimmune diseases to allergy and cancer." (PMID 26071023, 2015).
cancer (continued). "Neutrophils treated with a2NTD (a2Neuɸ) showed increased secretion of IL-1RA, IL-10, CCL-2 and IL-6 that are important mediators in cancer related inflammation." (PMID 26460736, 2015). "With PD-L1, adenosine, IL-10 and TGF-β we explored factors frequently produced by cancer cells that bind negative regulatory surface receptors expressed on cytotoxic T cells." (PMID 26510188, 2015). "Both IL-10 and TGF-β1 are characteristic of type 1 T regulatory cells and are frequently reported as immunoregulatory cytokines impairing cancer immune surveillance." (PMID 25749042, 2015). "Another strategy used by cancer cells to avoid the immune response consists of secreting immunosuppressive cytokines such as transforming growth factor β (TGF-β) and interleukin 10 (IL-10)." (PMID 24860567, 2014). "Both IL-10 and TGF-β are known to establish highly suppressive micro-environments that are suitable for cancer progression." (PMID 24639678, 2014). "It has been reported that the expression level of immunosuppressive cytokines, such as IL-10, was significantly higher than that of immunostimulatory cytokines, such as IL-2 and IFN-γ, in various cancer patients." (PMID 24358317, 2013). "Suppressed levels of Th1 cytokines (IFN-γ, IL-12, TNF-α) and elevated levels of Th2 cytokines (IL-4, IL-10, TGF-β) have been seen in patients with cancer, while the opposite pattern is seen in healthy individuals." (PMID 23730621, 2013). "Foxp3+, IL-10+, and TGF-β+ expressing cancer cells increased from early to late stages of disease compared to normal tissue." (PMID 23382847, 2013). "Next, we examined the expression of Foxp3 and immunosuppressive cytokines IL-10 and TGF-β in cancer cells." (PMID 23382847, 2013). "Immunofluorescence double staining indicated the expression of the immunosuppressive cytokines IL-10 and TGF-β in Foxp3+ expressing cancer cells (arrows)." (PMID 23382847, 2013). "The decrease in IL-10 secretion induced by anti-Rac3 siRNA can also be explained by the action of Rac3 on ERK-2/NF-κB signaling, but its role in cancer aggressivity has been reported to be due mainly to an immunosuppression and also to its angiogenic activity." (PMID 23388133, 2013). "It is important to note that IL-6 and IL-10, TNF-α, and IL-1β have been implied in the generation of the MDSCs, which are commonly found in cancer patients." (PMID 23616009, 2013). "In the present study, we confirmed a higher expression level of the examined genes (for PD-L1, Galectin-1, IL-6, IL-10, IDO, and TGF-β) in the cancer patients." (PMID 22496728, 2012). "In cancer patients, intraperitoneal/intravenous/subcutaneous administration of IL-12 increased peritoneal/serum levels of IFN-γ, TNF-α, IL-10, IL-8, VEGF, IP-10, and neopterin." (PMID 22383962, 2012). "Specifically, we found that the hematopoietin, TNF, IL1, IL10 and IL17 families of cytokines had a significant tendency to be hypomethylated in all five cancer types." (PMID 22970311, 2012). "MBS cytotoxicity and MBS-induced anticancer cytokines, TNF-α and IFN-β from cancer cells, and immunological cytokines, IL-4, IFN-γ, and IL-10 from peripheral mononuclear cells (PMNC) were assessed by MTS and ELISA assays." (PMID 23122182, 2012). "Also, a recent report has suggested that polymorphisms associated with low expression of anti-inflammatory IL-10 and TGF-β1 and immunomodulatory TNF-α, IFN-γ and IL-6 could be involved in the mechanisms of cancer progression and escape from immune surveillance." (PMID 18221542, 2008). "Additionally, three‐dimensional coculture models that simulate immunosuppressive conditions containing IL‐10 and CXCL1 have demonstrated enhanced cancer cell migration and progression." (PMID 41426206, 2026). "Among other genes that encode immune inhibitors, IL10, TGFBR1, and IDO1 exhibited a broadly negative correlation across most cancer types, aligning with the expression pattern of PEBP1/STK11." (PMID 40806276, 2025).